ABL1 (ABL proto-oncogene 1, non-receptor tyrosine kinase)
Diseases named in the same sentence as ABL1 in open-access papers (continued):
Sharing a sentence is not in itself a finding about the gene and the disease.
lung carcinoma (37 papers, 2007 to 2025). "Mutations in ABL1 identified in primary NSCLC tumors and a lung cancer cell line increase downstream pathway activation compared to wild-type ABL1." (PMID 38791306, 2024). "Mutational analysis was performed using web applications to predict the functional impact of the ABL1/2 mutations in these lung cancer cell lines." (PMID 26758680, 2016). "Consistent with structural modeling, we demonstrate that mutations in ABL1 identified in primary NSCLC tumors and a lung cancer cell line increase downstream pathway activation compared to wild‐type ABL1." (PMID 26758680, 2016). "Here, we provide data that supports a role for mutationally altered ABL1 as a novel genetic dependency in a subset of patients with lung cancer." (PMID 26758680, 2016). "Consistent with our modeling, we demonstrate that mutations in ABL1 in primary lung tumors and a lung cancer cell line increase the activity of ABL1 and mutated ABL1 proteins are primarily localized to the cytosol." (PMID 26758680, 2016). "Here, we identify somatically mutated ABL1 as a novel driver in lung cancer, where cells with ABL1 mutations are sensitive to ABL1 inhibitors, imatinib and dasatinib." (PMID 26758680, 2016). "All mutations occurred in the kinase domain and mutations in ABL1 identified in lung cancer cell lines and primary tumor tissues are depicted in Fig EV1." (PMID 26758680, 2016). "Consistent with our inhibitor data, depletion of ABL1 from both lung cancer cell lines harboring ABL1 mutations resulted in a significant reduction in cell viability compared with Beas‐2B cells." (PMID 26758680, 2016). "Since approximately 1–2% of patients with lung adenocarcinoma harbor ABL1 mutations, dasatinib or imatinib could represent a treatment option for 8,500–17,000 patients with lung cancer globally." (PMID 26758680, 2016). "We demonstrate that lung cancer cells harboring ABL1 mutations are sensitive to clinically relevant concentrations of imatinib and dasatinib and that these effects are specific to pharmacological inhibition of the mutated ABL1 as shown by the rescue experiments with a drug‐resistant variant of ABL1." (PMID 26758680, 2016). "However, our data indicate that only mutations in ABL1 would be pathogenic by promoting lung cancer cell survival and proliferation." (PMID 26758680, 2016). "Overall, this work demonstrates that somatically mutated ABL1 represents a genetic dependency that could be exploited therapeutically for a subset of patients with lung cancer." (PMID 26758680, 2016). "To determine whether the cell toxicity observed in lung cancer cells harboring ABL1 mutations can be attributed to inhibition of this kinase, we treated H1915 cells with ABL inhibitors and re‐expressed the drug‐resistant ABL1‐T315I mutant." (PMID 26758680, 2016). "Furthermore, we confirm that imatinib suppresses lung tumor growth in vivo, specifically in lung cancer cells harboring a gain‐of‐function (GOF) mutation in ABL1." (PMID 26758680, 2016). "Furthermore, ABL1 can promote metastasis of lung cancer cells carrying also EGFR or KRAS mutations." (PMID 33596996, 2021). "Therefore, increased cytoplasmic localization of ABL1‐R351W and ABL1‐G340L could have a similar function and contribute to the increased survival of lung cancer cells harboring these mutations." (PMID 26758680, 2016). "Control (SCR) and ABL1+ABL2 knockdown (AA) lung cancer cells were co-cultured with MSCs and then implanted in mice by intracardiac injection." (PMID 33119681, 2020). "In clinical lung cancer patient data, high expression levels of ABL1 and ABL2 and concomitant high transcription of TAZ/β-catenin targets correlate with shorter survival." (PMID 29734788, 2018). "Mutations in the analogous residue of ABL1 (L273M) and ErbB2 (L755S or P) have been described in patients with imatinib-resistant chronic myelogenous leukemia (CML) and solid tumors including gastric, breast, and lung cancers, respectively." (PMID 17973572, 2007).
lung carcinoma (continued). "To determine whether somatically mutated ABL1/2 may be required to maintain lung cancer cell survival, we treated this panel of NSCLC cancer cell lines harboring mutations in either ABL1 or ABL2 (H1915, H2110, H650, and H1623), with ABL inhibitors, and monitored cell viability." (PMID 26758680, 2016). "Both ABL1 and ABL2 kinases are required for metastasis of MSC-primed lung cancer cells to distal sites following intracardiac injection in mouse models." (PMID 34022881, 2021). "We previously showed that the ABL family of tyrosine kinases, ABL1 and ABL2, promote metastasis by breast and lung cancer cells in mouse models through activation of transcription factor networks." (PMID 33119681, 2020). "Efficient knockdown of ABL1 and ABL2 proteins and decreased phosphorylation of the ABL substrate p-CrkL was observed in both PC9 and HCC827 lung cancer cells." (PMID 33119681, 2020). "The ABL kinases, ABL1 and ABL2, promote invasion and metastasis of breast and lung cancer cells." (PMID 33119681, 2020). "Of these fusions, 16 (including ALK, ARAF, BRAF, FGFR1, FGFR3, RET, and ROS1) and 21 (including ABL1, GNAS, JAK2, and NRG1) were classified as either related to lung cancer, or as oncogenes that have not been reported in lung cancer, respectively." (PMID 36153311, 2022). "Depletion of ABL1 and ABL2 protein kinases in PC9-AA and HCC827-AA lung cancer cells impaired the increase of MMP9 but not MMP2 gelatinase activity induced by MSCs." (PMID 33119681, 2020).
melanoma (33 papers, 2005 to 2026). A malignant, usually aggressive tumor composed of atypical, neoplastic melanocytes. "Previously, we found that ABL kinases are activated by receptor tyrosine kinases such as EGFR, PDGFR, and IGF1R, and BRAF contributes to ABL1/2 activation in melanoma cells harboring BRAF-V600E." (PMID 36765910, 2023). "The expression of constitutively active ABL1/2 in melanomas has been described to be sufficient to promote resistance to vemurafenib, dabrafenib, MEK inhibitors, and their combination by inducing reactivation of MEK/ERK/MYC signaling." (PMID 34063141, 2021). "ABL1/2 are highly active in 40–60% of melanomas, and drive disease progression; however, their role in therapeutic resistance has not been explored." (PMID 33122628, 2020). "Increased ABL1 mRNA in primary melanomas correlates with activated ABL1 signaling and disease progression." (PMID 33122628, 2020). "Since ABL1/2 play important roles in driving melanoma progression and are activated by ERK pathway components (BRAF, ERK) in BRAF-mutant melanomas, we examined whether their activities are elevated during MEKi resistance in NRAS-driven melanomas." (PMID 36765910, 2023). "However, the contribution of ABL1/2 to MEKi resistance in NRAS-mutant melanomas represents a gap in our knowledge." (PMID 36765910, 2023). "During melanoma progression, ABL1/2 drive proliferation, survival, invasion, and metastasis by phosphorylating substrates including the CRK/CRKL adapter proteins, which results in induction of transcription factors and proteases that degrade the extracellular matrix." (PMID 36765910, 2023). "In contrast, other long-term MEKi acquired resistance cells were highly dependent solely on ABL1/2, which stabilized MYC and ETS1 proteins in an ERK-independent manner, and induced β-catenin nuclear localization to drive melanoma survival." (PMID 36765910, 2023). "Here, using both loss-of-function and gain-of-function approaches, we show that ABL1/2 and DDR1 are critical nodes during NRAS-mutant melanoma intrinsic and acquired MEK inhibitor (MEKi) resistance." (PMID 36765910, 2023). "ABL1 promotes melanoma invasion through STAT3-dependent MMP1 expression, while ABL2 promotes melanoma invasion by increased expression of MMP-1, MMP-3, and MT1-MMP independently of STAT3." (PMID 34022881, 2021). "ABL1 and ABL2 promote invasion and metastatic progression of melanomas in part by activating the transcription factors Ets1, Sp1, and NF-κB/p65 which induce expression of cathepsin ECM proteases." (PMID 34022881, 2021). "Gene mutations are often involved in tumorigenesis, the clustered deletions were found in ABL1, NOTCH1, RET, STK11, GNA11, and JAK3 genes in CRC, melanoma, and non-small cell lung cancers." (PMID 32850446, 2020). "Lastly, both ABL1 and ABL2 are essential for the invasive phenotype of melanoma cells, where ABL kinases were shown to directly regulate expression and activation of matrix metalloproteinases." (PMID 26758680, 2016). "These exciting data indicate that drugs targeting ABL1/2 and DDR1, many of which are FDA-approved, may be effective in conjunction with MEKi for patients with NRAS-mutant melanomas, a notoriously hard-to-treat class of patients." (PMID 36765910, 2023). "Thus, cotargeting ABL1/2 and DDR1 not only prevents ERK activation of downstream targets but also impacts other pathways involved in proliferation, survival, and melanoma progression." (PMID 36765910, 2023). "In summary, these exciting data indicate that targeting ABL1/2 and DDR1 in combination with MEKi may be an effective therapeutic regimen for patients with aggressive NRAS-driven melanomas, who have a poor prognosis and limited therapeutic options." (PMID 36765910, 2023).
melanoma (continued). "We used the lowest dose of SU6656 that efficiently reduces SFK activity in melanoma cells (10 μM), and we previously showed that this dose has no direct effect on ABL1 or ABL2 as it does not reduce their activities in cells that lack SFK expression." (PMID 33122628, 2020). "Importantly, ABL1 and MYC mRNAs are correlated in melanomas from patients prior to treatment (left) and in the TCGA dataset, and an even more significant correlation was observed in paired samples from the same patients following relapse on BRAFi or BRAFi/MEKi (right)." (PMID 33122628, 2020). "Thus, the data in this study provide the rationale for testing the use of drugs targeting ABL1/2 and DDR1 in combination with MEKi for patients with NRAS-mutant melanomas who have failed to respond to immunotherapy." (PMID 36765910, 2023).
acute leukemia (31 papers, 2012 to 2025). A clonal (malignant) hematopoietic disorder with an acute onset, affecting the bone marrow and the peripheral blood. "However, the identification of the BCR::ABL1 fusion (considered the hallmark of CML) as the primary oncogenic event through the clonal ontogeny of these cases of acute leukemia raises several concerns." (PMID 37895120, 2023). "This is a rare phenomenon and is distinct from the blastic transformation of CML and mixed phenotype acute leukemia (MPAL) with BCR::ABL1 fusion." (PMID 38633128, 2024). "Until the diagnosis is confirmed by the detection of BCR::ABL1 and the definition of the immunophenotype (lymphoid vs. myeloid), supportive therapy is administered as in acute leukemia (prevention of tumor lysis syndrome according to institutional standards)." (PMID 36707619, 2023). "The current studies demonstrate that most pediatric patients achieve complete cytogenetic remission and a BCR::ABL1 transcript level below 1% after acute leukemia induction chemotherapy with added TKI treatment." (PMID 36707619, 2023). "Then, we showed that the TAA/ABL1 levels from patients with MRD+ or relapsed acute leukemias were significantly higher than those of healthy control individuals." (PMID 36248870, 2022). "Third, CML diagnosis was based on the institutional diagnosis, and the diagnosis was not centrally reviewed, which could lead to unclear discrimination between BP-CML and acute leukemia with BCR::ABL1." (PMID 40088374, 2025). "Our ddPCR method of surveying acute leukemia burden by blood TAA/ABL1 may be valuable for other tumors that also express these TAAs, such as chronic leukemias, lymphomas, breast, lung, pancreas and colon cancer." (PMID 36248870, 2022). "We were able to directly cross-check the clinically most relevant RTK mutations in acute leukemia (i.e. FLT3-ITD, KIT D816V/Y, BCR/ABL1) transfected into an isogenic Ba/F3 background against a panel of leukemic cell lines harboring a corresponding RTK mutation." (PMID 23497317, 2013). "Notably, the number of mutations associated with BCR::ABL1-negative MPNs is smaller than those of acute leukemias and solid tumors, and the genetic mutation analyses play a significant role in confirming diagnosis and prognosis." (PMID 37629188, 2023). "We hypothesized that a blood-based multiplex ddPCR assay of WT1, BIRC5 (survivin), and PRAME as a ratio against homeostatic ABL1 would detect MRD in the majority of relapsed refractory acute leukemias after HCT, at levels exceeding those of healthy individuals." (PMID 36248870, 2022). "This study focuses on Philadelphia chromosome-positive acute leukemia patients, examining the correlation between BCR::ABL1 transcript levels (PCR-MRD) and a standardized flow cytometry-based MRD detection method (FCM-MRD) in B-ALL." (PMID 40076750, 2025). "Measurable residual disease in Philadelphia chromosome-positive disease, achieved with the BCR::ABL1 quantitative method, is the standard of care in CML and Ph+ acute leukemias." (PMID 40076750, 2025). "Subsequently, after undergoing acute leukemia therapy, both BCR/ABL1 (IS) levels and the proportion of CD56briCD38+ neutrophils dropped below the designated threshold values." (PMID 39559206, 2024). "Regarding acute leukemias, the BCR::ABL1 rearrangement can, therefore, be detected in AML arising from BC-CML, in de novo AML, and throughout the course of AML, as a secondary event." (PMID 37895120, 2023). "In patients with active acute leukemia after HCT (MRD+ or relapse; n=19), the blood levels of WT1/ABL1, PRAME/ABL1, and BIRC5/ABL1 exceeded healthy donors (p<0.0001, p=0.0286, and p=0.0064 respectively)." (PMID 36248870, 2022).
lymphoma (30 papers, 2008 to 2026). A malignant (clonal) proliferation of B- lymphocytes or T- lymphocytes which involves the lymph nodes, bone marrow and/or extranodal sites. "The expression of myeloid antigens CD13 and CD33 in B-lymphoblastic leukemia/lymphoma is typically observed in B-lymphoblastic leukemia/lymphoma with BCR::ABL1 fusion." (PMID 40227608, 2025). "B-lymphoblastic leukemia/lymphoma with BCR::ABL1 fusion has also been reported to exhibit a decreased expression of CD9 and CD81 when compared with cases of B-lymphoblastic leukemia/lymphoma without cytogenetic alterations or with other cytogenetic abnormalities." (PMID 40227608, 2025). "In the CSF + LM (lymphoma) vs. CSF − LM comparison, ITGB1, IL6, ABL1, CYCS, among others, were differentially observed and expressed in cancer cells." (PMID 35053611, 2022). "Because of a generalized lymphadenopathy noted at the time of diagnosis, a lymph node biopsy was also performed, which revealed a T-cell lymphoblastic leukemia/lymphoma, BCR/ABL1 positive, with clonal evolution." (PMID 30581639, 2018). "FOXP1 was already described as fused to either the PAX5 or the ABL1 gene in B-ALL, and to the immunoglobulin heavy chain locus in lymphomas." (PMID 24893616, 2014). "Bone marrow examination ultimately demonstrated T-lymphoblastic leukemia/lymphoma with an abnormal immature T-cell population and isolated ABL1 copy number gain in the absence of BCR::ABL1 fusion." (PMID 42281722, 2026).
myeloid leukemia (29 papers, 2010 to 2025). A clonal proliferation of myeloid cells and their precursors in the bone marrow, peripheral blood, and spleen. "Recently, via homologous recombination (HR) using CRISPR/Cas9 system, we introduced T315I gatekeeper mutation into the intrinsic BCR::ABL1 fusion gene in human Ph + myeloid leukemia cell lines and Ph + lymphoid leukemia cell line." (PMID 40208408, 2025). "In the present study, we successfully introduced F311I, T315I, and F311I/T315I mutations into the intrinsic BCR::ABL1 gene of TCCS (a TKI-sensitive human Ph+ myeloid leukemia cell line) using the CRISPR/Cas9 system." (PMID 39872583, 2024). "In the present study, to verify the utility of the CBE system, we first tried to introduce the T315I (ACT to ATT) mutation of the BCR::ABL1 fusion gene, which is the most important BCR::ABL1 mutation, in a human Ph+ myeloid leukemia cell line." (PMID 40342439, 2025). "Fundamental oncogenic properties of BCR::ABL1 in Ph + lymphoid leukemia cells must be identical to those in Ph + myeloid leukemia cells." (PMID 40208408, 2025). "We also observed downregulation of transcription factors such as Mga and Tcf4, and myeloid leukemia related genes including Pml, Abl1, and Bcl11a in terminally differentiated granulocytes in conjunction with the expression of a group of granulocyte-enriched miRNAs." (PMID 24886830, 2014). "However, in the whole transcriptome, the gene expression profile of Ph-positive myeloid leukemia cell lines and that of CML patients’ samples were substantially different from that of p210 or p190 BCR::ABL1 sublines and parental cells, regardless of whether cultured with GM-CSF or not." (PMID 35999358, 2023).
Parkinson disease (29 papers, 2012 to 2025). A progressive degenerative disorder of the central nervous system characterized by loss of dopamine producing neurons in the substantia nigra and the presence of Lewy bodies in the substantia nigra and locus coeruleus. "Overactivation of Abl1 has been linked to neurodegenerative diseases such as Parkinson’s and Alzheimer’s by facilitating α-synuclein accumulation and tau phosphorylation, suggesting a possible neuroprotective function of UPF in mitigating excitotoxic stress." (PMID 40422779, 2025). "Functional enrichment analysis showed that ABL1 was associated with Huntington's disease (P=1.12e − 08), amyotrophic lateral sclerosis (P=3.0e − 07), Alzheimer's disease (P=3.59e − 07), and Parkinson's disease (P=6.53e − 08)." (PMID 34484330, 2021). "ABL1 is present in its activated form in Parkinson’s disease (PD) patients as well as in preclinical models of the disease; furthermore, ABL1 has been reported to phosphorylate α-synuclein at Y39 and the E3 ligase Parkin, both of which are genetic risk factors for PD." (PMID 33117143, 2020). "In addition, ROS-mediated ABL1 plays key role in Parkinson's disease." (PMID 31396300, 2019).
acute promyelocytic leukemia (24 papers, 2009 to 2025). An aggressive form of acute myeloid leukemia (AML), characterized by arrest of leukocyte differentiation at the promyelocyte stage, due to a specific chromosomal translocation t(15;17) in myeloid cells. "Examples include tyrosine kinase inhibitors (TKI) in chronic myelogenous leukemia (CML) that block BCR::ABL1 kinase activity and differentiation therapy with all-trans retinoic acid (ATRA) in acute promyelocytic leukemia (APL) targeting the (PML::RARA) fusion." (PMID 37699001, 2023). "Importantly, PCR assays have been developed for three AML phenotypes: (i) acute promyelocytic leukemia (APL) (fusion gene PML::RARA); (ii) patients with NPM1 and CBF–AML (RUNX1::RUNX1T1 and CBFB::MYH11); and (iii) AML with fusion genes BCR::ABL1, KMT2::MLLT3, and DEK::NUP214." (PMID 37345204, 2023).